SMARCB1 (SWI/SNF related BAF chromatin remodeling complex subunit B1)
Diseases named in the same sentence as SMARCB1 in open-access papers (continued):
Sharing a sentence is not in itself a finding about the gene and the disease.
amyotrophic lateral sclerosis (2 papers, 2023 to 2024). Amyotrophic lateral sclerosis (ALS) is a neurodegenerative disease characterized by progressive muscular paralysis reflecting degeneration of motor neurons in the primary motor cortex, corticospinal tracts, brainstem and spinal cord. "A subset of our organoid data sets come from studies that performed diverse perturbations (22q11.2 deletion, SMARCB1 knockdown, exposure to Alzheimer’s serum, amyotrophic lateral sclerosis patient-derived organoids)." (PMID 39621752, 2024). "A subset of our organoid datasets come from studies that performed diverse perturbations (22q11.2 deletion, SMARCB1 knockdown, exposure to Alzheimer’s serum, SETBP1 point mutations, amyotrophic lateral sclerosis patient-derived organoids)." (PMID 37034757, 2023).
ataxia telangiectasia (2 papers, 2018 to 2023). Ataxia-telangiectasia is the association of severe combined immunodeficiency (affecting mainly the humoral immune response) with progressive cerebellar ataxia. "WSE correlated with mutations in the genes SMARCB1 (p=0.002), Ataxia telangiectasia mutated (p=0.004), Kinase Insert Domain Receptor (p=0.006), and were borderline significant in RET and EGFR exon." (PMID 30093964, 2018).
chondrosarcoma (2 papers, 2014 to 2024). A malignant cartilaginous matrix-producing mesenchymal neoplasm arising from the bone and soft tissue. "However, as we showed, metastatic nodal seminoma cells were strongly positive for SMARCB1 by IHC, suggesting that loss of SMARCB1 in the STM chondrosarcoma represents an acquired genetic or epigenetic phenomenon rather than a germline event." (PMID 38236556, 2024). "Unlike “typical” cases of conventional head and neck chondrosarcoma, the STM chondrosarcoma showed loss of SMARCB1 expression, focal to diffuse immunostaining for epithelial markers, including EMA, CAM 5.2 and CK AE1/AE3, and 12p duplication with absence of IDH1/2 mutations." (PMID 38236556, 2024). "Interestingly, the STM chondrosarcoma of the current patient exhibited uniform negativity for SMARCB1 by IHC in the sarcomatous cells but retained expression in non-neoplastic background cells." (PMID 38236556, 2024).
endometrioid carcinoma (2 papers, 2022). "These tumors arise from endometrioid carcinomas, most commonly in a MMR-deficient (MMRd) background, by acquiring the following mutually exclusive alterations in the undifferentiated component: the co-mutation of ARID1B/ARID1A, SMARCA4 (BRG1) or SMARCB1 (INI1)." (PMID 35053578, 2022).
epilepsy (2 papers, 2019 to 2023). A brain disorder characterized by episodes of abnormally increased neuronal discharge resulting in transient episodes of sensory or motor neurological dysfunction, or psychic dysfunction. "Interestingly, among multiple CRF genes, only SMARCA2, SMARCB1, ACTL6B and KDM5C have been previously associated with epilepsy, and some other members of this cluster (e.g., SMARCC1, SMARCC2, SMARCA4 and WRD5) are only cursorily mentioned among epilepsy candidate genes." (PMID 36982355, 2023).
esophageal cancer (2 papers, 2018 to 2019). A primary or metastatic malignant neoplasm involving the esophagus. "In this study, we describe a case of esophageal carcinoma with undifferentiated components and rhabdoid features that was exclusively positive for vimentin and SMARCB1 and associated with prolonged survival." (PMID 30649642, 2019). "In this study, we describe a case of esophageal carcinoma with undifferentiated components and rhabdoid features that was exclusively positive for vimentin and SMARCB1 in a patient with prolonged survival." (PMID 30649642, 2019).
follicular carcinoma (2 papers, 2020 to 2024). "Recently, one of 35 patients with follicular thyroid cancer was found to have the SMARCB1 mutation." (PMID 32380731, 2020).
hemoglobinopathies (2 papers, 2025). "Recently, extremely atypical and uncommon tumors that share morphological and phenotypic characteristics with RMC, but occur in patients without hemoglobinopathy, have been reported and temporarily termed “unclassified RCC with medullary phenotype and SMARCB1 deficiency”." (PMID 40777608, 2025).
hepatocellular carcinoma (2 papers, 2021 to 2025). A malignant tumor that arises from hepatocytes. "We show NELFE is oncogenic in hepatocellular carcinoma (HCC) by undergoing liquid-liquid phase separation (LLPS) with SMARCB1 to modulate chromatin accessibility to downregulate pro-apoptotic genes through Pol II pausing while activating pro-growth signals to promote HCC progression." (PMID 40313774, 2025).
Hydrocephalus (2 papers, 2023 to 2025). Hydrocephalus is an active distension of the ventricular system of the brain resulting from inadequate passage of CSF from its point of production within the cerebral ventricles to its point of absorption into the systemic circulation. "Shared abnormalities were growth delay, which has been observed especially in SMARCB1 pathogenic variants, and hydrocephalus, which has only recently been described as a common prenatal characteristic in ARID1A pathogenic variants (but not in SMARCB1 variants)." (PMID 37219662, 2023). "Of 15 Smarcb11148del/1148del mice and 15 Smarcb1+/+ mice observed postnatally over a period of 50 days, 9 Smarcb11148del/1148del mice and 0 Smarcb1+/+ mice showed externally visible hydrocephalus (average observational time point: 32 days [15; 47 days]) (Online Resource 3c)." (PMID 37219662, 2023).
hypertrichosis (2 papers, 2019 to 2021). Excessive hair growth anywhere on the body. "Cryptorchidism, sparse scalp hair, and hypertrichosis were all seen in 50% of SMARCB1 patients (7/14, 3/6 males for cryptorchidism)." (PMID 34205270, 2021).
large cell NEC (2 papers, 2021 to 2022). "In contrast to SMARCB1-deficient carcinomas, and because of their cell morphology and immunophenotype, most SMARCA4-deficient tumors have been initially misclassified as small or large cell neuroendocrine carcinomas and, less frequently, as SNUC or teratocarcinosarcoma." (PMID 35307773, 2022).
leiomyoma (2 papers, 2017 to 2025). A well-circumscribed benign smooth muscle neoplasm characterized by the presence of spindle cells with cigar-shaped nuclei, interlacing fascicles, and a whorled pattern. "Whether germline SMARCB1 PVs may also predispose to leiomyomas remains unclear." (PMID 40794298, 2025). "So far, only one patient with SMARCB1-related SWN has been reported with a leiomyoma of the cervix uteri." (PMID 40794298, 2025).
metastatic carcinoma (2 papers, 2019 to 2020). A carcinoma which has spread from the original site of growth to another anatomic site. "Primary or metastatic carcinomas are positive for cytokeratin and EMA and retain SMARCB1 (INI1) expression." (PMID 32316685, 2020). "The metastatic carcinoma showing epithelial connections was diffusely positive for AE1/AE3, CAM 5.2, EMA, and SMARCB1." (PMID 30649642, 2019).
microcephaly (2 papers, 2019 to 2023). A congenital or acquired developmental disorder in which the circumference of the head is smaller than normal for the person's age and sex. "Heterozygous Smarcb1 disruption in neural stem/progenitor cells led to microcephaly, brain midline abnormalities and choroid plexus hyperplasia." (PMID 37219662, 2023). "However, microcephaly and growth impairment, two features typically associated with SMARCB1-CSS and present in all Smarcb1 mutant mice, are not characteristic for these four patients." (PMID 31273213, 2019).
Multiple myeloma (2 papers, 2019 to 2025). "We found that treatment of the SMARCB1 deficient cell lines with either bortezomib or MLN2238 led to inhibition of the proteasome to a similar extent observed when the multiple myeloma cell line RPMI8226 was treated." (PMID 30860482, 2019). "We found that our SMARCB1 deficient cell lines exhibited single digit nanomolar sensitivity to proteasome inhibition similar to that observed in the multiple myeloma cell line RPMI8226." (PMID 30860482, 2019). "(a) Multiple myeloma cell lines and SMARCB1-deficient lines are similarly sensitive to proteasome inhibitor, MLN2238." (PMID 30860482, 2019). "Although in multiple myeloma cells, tumor regression has been observed in xenografts following treatment with MLN2238, we found that treatment with MLN2238 of SMARCB1 deficient xenografts led to a cytostatic response." (PMID 30860482, 2019).
neuroendocrine neoplasm (2 papers, 2021 to 2024). Endocrine tumors, also referred to as neuroendocrine tumors (NETs), are defined by a common phenotype which is characterized by the expression of general markers (neuron specific enolase, chromogranin, synaptophysin) and hormone secretion products. "SMARCB1 loss was detected in most of these cases (9/11), including eight SCCs and one mixed neuroendocrine/non-neuroendocrine neoplasm (MiNEN), composed of a LCNEC and a NKSCC." (PMID 34638515, 2021).
Pleural effusion (2 papers, 2024 to 2025). The presence of an excessive amount of fluid in the pleural cavity. "Thus, comparative INI-1 stainings and SMARCB1 fluorescence in situ hybridisations (FISHs) of the primary tumour, the lymph node metastasis, and the pleural effusion were performed." (PMID 38786326, 2024).
scoliosis (2 papers, 2018 to 2019). A congenital or acquired spinal deformity characterized by lateral curvature of the spine. "Severe scoliosis is also frequently observed in patients with SMARCB1 mutations." (PMID 30123105, 2018). "However, the patients with the SMARCB1 mutation additionally showed CNS malformations, respiratory complications, and scoliosis, as well as limb and facial features that differed from the molecularly proven DOORS syndrome patients in their study." (PMID 30123105, 2018).
seminoma (2 papers, 2024 to 2025). A radiosensitive malignant germ cell tumor found in the testis (especially undescended), and extragonadal sites (anterior mediastinum and pineal gland). "However, Seminomas are less malignant and more sensitive to radiotherapy compared with the SMARCB1-deficient tumor,and patients generally have a good prognosis." (PMID 40115023, 2025).
sinus (2 papers, 2024 to 2025). "It is characterised by the absence of nuclear SMARCB1 expression and typically presents at advanced stages due to non-specific symptoms resembling benign conditions such as nasal polyps or sinusitis." (PMID 39925590, 2025).
thymoma (2 papers, 2017 to 2022). A neoplasm arising from the epithelial cells of the thymus. "Only two B3 thymomas had a mutation in noncoding regions of the SMARCB1 and STK11 gene respectively." (PMID 27844328, 2017). "Two (10%) B3 thymomas had a mutation in non-coding regions of SMARCB1 and STK11." (PMID 35884448, 2022).
anaplastic thyroid cancer (1 paper, 2020). "Although it was reported that SMARCB1 mutations were acquired in about 6% of anaplastic thyroid cancer cases, somatic mutation of the SMARCB1 gene is very uncommon in differentiated thyroid cancer." (PMID 32380731, 2020). "Of 57 patients with fatal non-anaplastic thyroid cancer, mutations in SMARCB1 were identified in 4% of the cohort." (PMID 32380731, 2020). "The histology type of most cases with somatic SMARCB1 mutations was anaplastic thyroid cancer." (PMID 32380731, 2020).
breast tumors (1 paper, 2021). "Analyses of human breast tumors indicate that SOX4 mRNA is uniformly overexpressed in basal-like tumors relative to adjacent normal tissue along with the SWI/SNF catalytic subunit SMARCA4 and SMARCB1 SMARCC1, SMARCD2, and ACTL6A, which encode for the essential subunits of this complex." (PMID 33837205, 2021).
cholangiocarcinoma (1 paper, 2014). A carcinoma that arises from the intrahepatic biliary tree (intrahepatic cholangiocarcinoma) or from the junction, or adjacent to the junction, of the right and left hepatic ducts (hilar cholangiocarcinoma). "Alterations in chromatin remodeling genes (ARID1A, BAP1, IDH1, IDH2, PBRM1, SMARCB1) were found in 30.7% (47/153) of cancers in our series, confirming recent reports on the significant involvement of these genes in cholangiocarcinoma." (PMID 24867389, 2014).
chondroid chordoma (1 paper, 2023). A slow-growing malignant bone tumor arising from the remnants of the notochord and occurring in the base of the skull. "None of conventional/chondroid chordoma cases displayed complete loss of SMARCB1/INI1 loss." (PMID 37456229, 2023).
Chordoid Meningioma (1 paper, 2022). A WHO grade II, usually recurring meningioma characterized by the predominance of tissues that are histologically similar to chordoma. "Genetically, previous studies found that chordoid meningiomas had sparce NF2, TRAF7, KLF4, SMO, AKT1 and SMARCB1 mutations common to non-chordoid meningioma." (PMID 35440040, 2022).
colorectal adenocarcinoma (1 paper, 2018). The most common type of colorectal carcinoma. "Loss of expression of SMARCB1 has been reported in colorectal adenocarcinomas and has been associated with higher histological grade, larger tumor size, poor overall survival, MSI, and the BRAF V600E mutation." (PMID 30108113, 2018).
cutaneous T-cell lymphoma (1 paper, 2024). "We next performed immunohistochemical analysis of SMARCB1 expression in 15 cases of mycosis fungoides (MF), a type of cutaneous T-cell lymphoma." (PMID 39362842, 2024).
endometriosis (1 paper, 2022). The growth of functional endometrial tissue in anatomic sites outside the uterine body. "Most notably, ARID1A in endometriosis-related OC, SMARCA4, and SMARCB1 in hypercalcemic type small cell ovarian carcinoma (SCCOHT), ACTL6A, CHRAC1, RSF1 amplification in high-grade serous OC." (PMID 36430148, 2022).
gliomatosis cerebri (1 paper, 2023). A diffuse glial tumor which infiltrates the brain extensively, involving more than two lobes. "In Case 2 with H3K27M-mutated DMG (and BRAFV600E and SMARCB1 alterations), and Case 3 with gliomatosis cerebri (EGFR overexpression and CDKN2A deletion) in reduced clinical condition, local re-irradiation and targeted therapy (with or without chemotherapy and/or immunotherapy) were proposed." (PMID 36720762, 2023).
HCMV infection (1 paper, 2012). "We investigated whether SMARCB1 was recruited to these sites during HCMV infection by assessing intracellular localization of SMARCB1 in mock and HCMV-infected fibroblast cells at immediate –early (5–12 hpi), early (24 hpi) and late (48 and 72 hpi) time points of infection." (PMID 22479537, 2012).
Hypertension (1 paper, 2022). The presence of chronic increased pressure in the systemic arterial system. "Our study found that multiple SNPs in SMARCB1 gene (rs5751740, rs5751741, rs5760038, rs5760046, rs5760057, rs5996620) are both related to high TG level and hypertension." (PMID 35484552, 2022).
large cell lung carcinoma (1 paper, 2022). "Therefore, this case probably fits best in the category of large cell lung carcinoma with an additional SMARCB1 alteration as a later event in the evolution of this tumor." (PMID 35864317, 2022).
liver tumors (1 paper, 2022). "In studies conducted before the identification of SMARCB1 mutations with consecutive loss of INI1-positivity in immunohistochemistry, the classification of liver tumors as MRTL were solely based on cytomorphology (i.e., predominance of rhabdoid tumor cells)." (PMID 35053437, 2022).
Meningioangiomatosis (1 paper, 2020). A rare vascular malformation in the cerebral cortex and overlying leptomeninges. "Immunophenotypically, the meningioangiomatosis component in these cases exhibited staining with SMARCB1, but this expression was lost in the dedifferentiated sarcomatous component." (PMID 31161239, 2020). "In at least one case report, a patient developed a malignant SMARCB1-deficient desmoplastic spindle cell sarcoma associated with pre-existing sporadic meningioangiomatosis in the absence of germline SMARCB1 or NF2 mutations." (PMID 31161239, 2020).
myeloid leukemia (1 paper, 2020). A clonal proliferation of myeloid cells and their precursors in the bone marrow, peripheral blood, and spleen. "Recently, their involvement in maintaining oncogenic gene expression program in myeloid leukemia, in particular for the tumor suppressor SMARCB1, have been demonstrated." (PMID 32471360, 2020).
Neoplasm of the lung (1 paper, 2025). Tumor of the lung. "Through comprehensive IHC profiling, recurrence of plasmacytic myeloma was ruled out, ultimately leading to the diagnosis of SMARCB1 (INI-1)-deficient intrathoracic neoplasm of the lung." (PMID 40291911, 2025).
neuroepithelial tumors (1 paper, 2024). "As such, EWSR1-PLAGL1 neuroepithelial tumors are a tumor type in which acquired inactivation of SMARCB1 and development of AT/RT features may occur and lead to clinical progression." (PMID 39228008, 2024).
Noonan syndrome (1 paper, 2022). Noonan Syndrome (NS) is characterized by short stature, typical facial dysmorphism and congenital heart defects. "There is also a need to clarify the overlap with allelic conditions such as LZTR1-related Noonan syndrome as well as Coffin-Siris and rhabdoid tumour predisposition with SMARCB1 variants." (PMID 35361920, 2022).
oesophageal adenocarcinoma (1 paper, 2020). "Almost nothing is known about the other familiar members of the SWI/SNF complexes, SMARCA2 (BRM), SMARCA4 (BRG1) and SMARCB1 (INI1), in oesophageal adenocarcinoma (EAC)." (PMID 31906887, 2020).
oligodendroglioma (1 paper, 2023). A well-differentiated (WHO grade II), diffusely infiltrating neuroglial tumor, typically located in the cerebral hemispheres.
ovarian tumors (1 paper, 2022). "This case report emphasizes the importance of performing INI1/SMARCB1 IHC on undifferentiated ovarian tumors in young patients that show a retained SMARCA4 expression to determine the correct diagnosis of SCCOHT." (PMID 35200537, 2022).
papillary thyroid cancer (1 paper, 2020). "Analysis of The Cancer Genome Atlas database revealed that SMARCB1 underexpression was associated with the follicular variant subtype and aneuploidy in papillary thyroid cancer." (PMID 32380731, 2020). "In agreement with prior observations, we found that follicular cancer tended to have a higher frequency of loss of INI1 expression (p = 0.073) in the present study, and the follicular variant of papillary thyroid cancer was significantly associated with SMARCB1 underexpression in the TCGA dataset." (PMID 32380731, 2020). "We found that SMARCB1 appeared downregulated in the invasive part of papillary thyroid cancer, while the tumor center retained the same expression level as normal thyroid tissues." (PMID 32380731, 2020). "Papillary thyroid cancer with SMARCB1 underexpression was more likely to be the follicular variant." (PMID 32380731, 2020).
papilloma (1 paper, 2019). A benign epithelial neoplasm that projects above the surrounding epithelial surface and consists of villous or arborescent outgrowths of fibrovascular stroma. "The Smarcb1 mutant mouse model combines features of both neurodevelopmental defects and a benign lesion of increased tissue mass (CP hyperplasia/papilloma)." (PMID 31273213, 2019). "We have generated the first Smarcb1 mutant mouse model that shows features of SMARCB1-CSS and SMARCB1-related ID-CPH and exhibits a benign lesion of increased tissue mass (CP hyperplasia/papilloma)." (PMID 31273213, 2019).
Sézary syndrome (1 paper, 2023). "Other SWI/SNF genes recurrently altered in CTCLs are SMARCE1 and SMARCD2 (each amplified in 20% Sézary syndrome patients, N = 25), ARID2 (deleted in 8% Sézary syndrome patients, N = 25), and SMARCB1 (point mutation frequency ~ 3%, combined N = 433)." (PMID 36810086, 2023).